EGFR (epidermal growth factor receptor)
Diseases named in the same sentence as EGFR in open-access papers (continued):
Sharing a sentence is not in itself a finding about the gene and the disease.
lung cancer (continued). "Similarly, restoration of E-cadherin increased the sensitivity to EGFR-TKI in lung cancer cell lines." (PMID 22752005, 2012). "(b) Seven years after the importance of determining the mutational status of EGFR in lung cancer was first demonstrated, there is still no standardized approach to performing this mutational analysis." (PMID 22952784, 2012). "It has been shown that targeting EGFR is able to reduce lung cancer burden in animal studies." (PMID 22457794, 2012). "Therefore, it is interesting to determine if MUC1 is also involved in carcinogen-induced EGFR activation for lung cancer development." (PMID 22457794, 2012). "Furthermore, EMT has been reported to be related to reduced sensitivity and acquired resistance to epidermal growth factor tyrosine kinase inhibitors (EGFR-TKI) in lung cancer cells." (PMID 22752005, 2012). "The combination of a potent, irreversible kinase inhibitor such as afatinib, with EGFR-specific siRNAs should be further investigated as a new strategy in the treatment of lung cancer and other EGFR dependent cancers, including those with downstream resistance mutations." (PMID 22436374, 2012). "In clinical lung cancers, K-RAS mutations confer resistance to EGFR-TKIs." (PMID 22923130, 2012). "Our data also build on a recent report by Rai and co-workers in which delivery of miR-7 to EGFR inhibitor-resistant lung cancer cells suppressed growth in vitro and in vivo, an effect that was associated with decreased expression of EGFR as well as its downstream kinases RAF1 and IRS1." (PMID 23115635, 2012). "It has been recently demonstrated that the EGFR inhibitors gefitinib and erlotinib enhance the susceptibility to NK cell mediated lysis of A549, NCI-H23 and SW-900 lung cancer cell lines by the induction of ULBP1 (a ligand of the NK cell activation receptor NKG2D)." (PMID 23234355, 2012). "However, on the other hand, inactivating NOTCH1 or ADAM17 resulted in substantial cell death, while EGFR inhibition predominantly induced cell arrest in lung cancer." (PMID 22239941, 2012). "It is well known that genetic alternation of epidermal growth factor receptor (EGFR) plays critical roles in tumorgenesis of lung cancer and can predict outcome of non-small-cell lung cancer treatment, especially the EGFR tyrosine-kinase inhibitors (EGFR-TKIs) therapy." (PMID 23009178, 2012). "CARMA3 could serve as a potential companion drug target, along with NF-kB and EGFR in EGFR-mutant lung cancers." (PMID 22615840, 2012). "Gefitinib targets the EGFR for therapeutic drug intervention within lung cancer." (PMID 22685658, 2012). "The OS of the 225 lung cancer patients who did not receive gefitinib, with follow-up until June 30, 2011, was studied in reference to the EGFR polymorphism status." (PMID 23226726, 2012). "As overexpression of CARMA3 proteins induces robust NF-kB activation, CARMA3 and NF-kB may serve as potential companion drug targets along with EGFR in EGFR-mutant lung cancer." (PMID 22615840, 2012). "Further proving that mutations in the RAS-RAF-MAPK pathway often have one hit per tumor, these tumors had no other known mutations in genes often mutated in lung cancer, such as EGFR, KRAS, HER2, or PIK3CA, or BRAF." (PMID 22928112, 2012). "In most of the cases, EGFR mutations are nonoverlapping with other oncogenic mutations in lung cancer." (PMID 26316937, 2012). "In one series of Taiwanese patients with lung cancer TWIST1 expression was shown in 36% of samples but the relation with EGFR mutational status was not reported." (PMID 22272264, 2012). "Although the role of EGFR in lung cancer progression is well known, whether and how EGFR contributes to lung epithelial cell transformation is less clear." (PMID 22457794, 2012). "Recently, a clinical trial was conducted to investigate whether there would be any additional clinical benefit with the addition of systemic chemotherapy to an EGFR TKI in lung cancer patients." (PMID 22970367, 2012).
lung cancer (continued). "Moreover, forced expression of AXL in EGFR mutant lung cancer cell lines that are sensitive to erlotinib induced erlotinib resistance through the kinase activity of AXL." (PMID 22970367, 2012). "Although it is well known that epidermal growth factor receptor (EGFR) is involved in lung cancer progression, whether EGFR contributes to lung epithelial cell transformation is less clear." (PMID 22457794, 2012). "Though we did not assess the epidermal growth factor receptor (EGFR) mRNA or protein expression in bronchial epithelial cultures, we speculate that increased GRPR expression contributes to lung cancer through EGFR-dependent and/or -independent mechanisms." (PMID 22296774, 2012). "For example, adding a MET inhibitor may be beneficial to EGFR mutant lung cancer patients whose tumors harbor MET amplification as a mechanism of EGFR TKI resistance." (PMID 22970367, 2012). "In our most recent manuscript, we explored the involvement of MET-modulated miR-221 and miR-222 in the development of de novo and acquired resistance of lung cancer cells to tyrosine kinase inhibitors, such as gefitinib, the first line of treatment for EGFR-positive lung cancer patients." (PMID 22348396, 2012). "Specific targeting of EGFR is already used in patients with metastatic colon and lung cancer." (PMID 24213116, 2011). "Epidermal growth factor receptor (EGFR) is closely correlated with the progression of lung cancer." (PMID 21645455, 2011). "Mutations in exons 18 - 21 of the EGFR gene investigated by PCR were either absent or present in only rare breast cancer patients, such mutations being much frequent in lung cancer." (PMID 21702909, 2011). "Because it is tightly associated with never-smokers, EGFR mutations are common targets for biomarker discovery for lung cancers in never-smokers but not in smokers." (PMID 24212941, 2011). "Lastly, this strategy may also be feasible in other tumors with aberrant EGFR signaling, such as brain and lung cancers." (PMID 21912620, 2011). "Molecularly targeted agents, such as epidermal growth factor receptor (EGFR)–tyrosine kinase inhibitors (TKIs), have been found to provide substantial clinical benefit in lung cancer patients, and MET is considered a molecular target of potential relevance to lung cancer." (PMID 21847121, 2011). "Deregulation of the phosphatidylinositol 3-kinase pathway has been shown to be an early event in the development of lung cancer, and altered signalling via the epidermal growth factor receptor may lead to the development of lung cancer in patients with COPD." (PMID 29090135, 2011). "We examined the published literature on the analytic validity, clinical validity, and clinical utility of EGFR mutational testing in guiding first-line therapy use of erlotinib to treat advanced NSCLC and we briefly summarized the current lung cancer screening guidelines." (PMID 21743846, 2011). "For example one could combine Fus1 nanocarrier with the epidermal growth factor receptor (EGFR) kinase-targeted inhibitors for treatment of lung cancer." (PMID 21490751, 2011). "Thus, there is a strong rational for dual targeting of IGF-1R and ErbB2 or EGFR in breast or other carcinomas such as lung cancer." (PMID 24212944, 2011). "Germ-line polymorphisms for EGF, EGFR, Cox2, Cyclin D1, and FCGR2A may also be significant predictive markers for treatment response in lung cancer, but data from patients with cervical tumours treated with EGFR inhibitors is critically needed." (PMID 22091418, 2011). "Therefore, when using the EGFR mutant-specific antibodies for detecting EGFR mutant lung cancers, side by side IHC with total EGFR antibody is also necessary for the interpretation of the IHC result of mutation-specific antibody." (PMID 21858063, 2011). "For instance, EGFR pathway is frequently activated by gene mutations in nonsmoker lung cancers, while mutations of KRAS often occur in smoker lung cancer." (PMID 22174919, 2011).
lung cancer (continued). "Studies with first-line EGFR TKIs in advanced lung cancer have been recently reported." (PMID 21444946, 2011). "This suggested that an understanding of the mechanism by which smoke activates EGFR might elucidate lung cancer pathogenesis and prompted us to identify mechanisms linking EGFR activation to tobacco smoke." (PMID 21423656, 2011). "TAp63γ has been reported to repress EGFR promoter activity in H1299 lung cancer cells." (PMID 22053213, 2011). "In lung cancer therapy, anti-angiogenic or anti-inflammatory agents show widespread efficacy across many cancer types, while inhibition of the EGF receptor (EGFR) is mainly effective in the NSCLC sub-population containing activating EGFR mutations." (PMID 21699731, 2011). "However, following the increase in usage of EGFR-TKIs in lung cancer therapy, a significantly higher incidence of life-threatening drug induced ILD in Japanese patients than that of patients in the rest of the world was reported." (PMID 21791074, 2011). "Spatial and temporal observation of the EGFR gene status could help in making an appropriate therapeutic decision for locoregional and systemic management of lung cancer." (PMID 22108465, 2011). "In addition to EGFR-targeting therapies, new molecular insights into lung cancer development currently have emerged." (PMID 21811254, 2011). "However, the significance of EGFR protein expression is controversial in other tumors, such as lung carcinomas." (PMID 21403829, 2011). "Epidermal growth factor receptor is one of the most common proto-oncogenes in lung cancer." (PMID 20859290, 2010). "However, we did not detect an obvious correlation between mutational expression of EGFR, BRAF, PI3KI, or KRAS and sensitivity to AZD6244 or MK2206 in the lung cancer lines we tested." (PMID 21124782, 2010). "In conclusion, our results demonstrate that SH2 profiling can recognize distinct patterns of EGFR signaling in lung cancer cells, and more broadly provides a straightforward and comprehensive approach to profile the global state of tyrosine phosphorylation signaling in tumors." (PMID 20976048, 2010). "The epidermal growth factor receptor (EGFR) that regulates cell proliferation, apoptosis, angiogenesis and tumor invasion is over-expressed or in certain cases affected by oncogenic mutations in NSCLC and is one of the major target for lung cancer therapy." (PMID 21532835, 2010). "The data provided in this report suggest that in addition to the identified resistance factors in lung cancer, Met activity may be a regulator of response to EGFR inhibitors in breast cancers." (PMID 20624308, 2010). "We selected the lung cancer cell line A549, which harbors genomic amplification of EGFR and HER-2." (PMID 20459769, 2010). "EGFR mutations in lung cancer are more frequent in never smokers and are exclusive with KRAS mutations." (PMID 21151896, 2010). "We thus hypothesize that c-CBL mutations might contribute to the oncogenic potential of MET and EGFR in lung cancer." (PMID 20126411, 2010). "The tailored use of EGFR-TKI therapy has been pioneered in the area of lung cancer." (PMID 20961434, 2010). "Potentially those key regulators involved in the CSC programming may act as effective targets for drug development to overcome the primary resistance to anticancer drugs including resistance to EGFR-targeted therapy in lung cancer." (PMID 21165163, 2010). "Recent studies have demonstrated that activating mutations in the EGFR tyrosine kinase domain occur much more frequently in lung cancers in non and never smoking patients." (PMID 20546590, 2010). "In addition to FISH, we evaluated the membrane expression of total and phosphorylated HER2 and EGFR using IF on the breast and lung cancer cell lines spiked into blood and recovered with the CPK." (PMID 20461092, 2010). "EGFR and c-Met are both overexpressed in lung cancer and initiate similar downstream signaling, which may be redundant." (PMID 21390244, 2010).
lung cancer (continued). "In the second case, the EGFR pathway is found significantly involved in the difference between lung cancer patients with and without EGFR mutation." (PMID 20809931, 2010). "We hypothesised that targeting both the tumour and its vasculature by VEGFR and EGFR blockade would improve lung cancer treatment, particularly when combined with radiation therapy." (PMID 20628392, 2010). "Growing evidence from miRNA studies may help clarify the role of the EGFR network in lung cancer oncogenesis and provide a clue to solve EGFR—TKI resistance problems." (PMID 20859290, 2010). "E.g. one study of CTCs from lung cancer patients was able to identify EGFR T790M in CTCs of some patients and progression-free survival was shorter as one might expect in patients with than without T790M on erlotinib." (PMID 21165163, 2010). "Interestingly, a good response to EGFR antagonists in head and neck and lung carcinomas with expression of MAPKs has been observed." (PMID 20664595, 2010). "High EGFR gene copy number/amplification has been reported in 7% to 45% of lung carcinomas." (PMID 20637128, 2010). "This may be consistent with previous reports of poor prognosis of lung carcinomas with higher EGFR copy numbers." (PMID 20637128, 2010). "Furthermore, a recent study has revealed Gab1 not only as a convergence point between c-MET and EGFR pathways, but also suggests that Gab1 cooperates with MET amplification in lung cancer cells, which have become resistant towards the EGFR inhibitor gefitinib." (PMID 19737390, 2009). "However, the aim of our study was to focus on the effect of exemestane on aromatase activity and EGFR signalling, when used at a dose with a significant effect on lung cancer cell proliferation." (PMID 19930708, 2009). "Because of its pivotal role in lung cancer, we examined the EGFR pathway in greater detail." (PMID 19946374, 2009). "The EGFR signal transduction pathway regulates essential cellular functions, and appears to play a central role in the etiology and progression of numerous epithelial malignancies, including lung cancer." (PMID 19702827, 2009). "A recent commentary synthetically addresses the question of the ideal method for EGFR mutation testing in lung cancer, but no such data are available for K-Ras." (PMID 19293811, 2009). "Thus, the identification and characterization of potential factors that regulate EGFR pathways are critical to our understanding of lung cancer development and progression." (PMID 19702827, 2009). "In contrast to a previous report in lung cancer, we did not observe an association between chromosome 7 polysomy and EGFR overexpression." (PMID 19061514, 2008). "In this study, we sought to define the role of MET signalling in EGFR-TKI-resistant lung cancer." (PMID 19238632, 2008). "Evidence from lung cancer, pancreatic cancer, melanoma and head and neck cancer suggest that ErbB3-dependent signalling mechanisms are important for not only disease progression, but also resistance to EGFR-targeted therapies." (PMID 18841159, 2008). "The induction of a combination of hTERT mRNA and EGFR mRNA into the early diagnosis of lung cancer may improve the follow-up of patients." (PMID 21892326, 2008). "Taken together, our study supports the hypothesis that MET may be targeted to circumvent T790M-EGFR-mediated intrinsic or acquired resistance to EGFR-TKI (erlotinib) in lung cancer." (PMID 19238632, 2008). "The characteristics of eight OMIDI paired doublets in the EGFR gene in lung cancer." (PMID 19005564, 2008). "Although lung cancers having EGFR mutations were reported to be responsive to gefitinib therapy, about 10% of lung cancers without EGFR mutations were also susceptible to this therapy." (PMID 18950515, 2008). "It is possible that in EGFR mutant lung cancers there is already maximal activation of the PI3K/Akt/mTOR signalling pathway and thus an LKB1 mutation may not be required to further potentiate this signalling pathway." (PMID 18594528, 2008).
lung cancer (continued). "We first examined the expression pattern of MET and EGFR in lung cancer cell lines." (PMID 19238632, 2008). "Taken together, these data provide support that cooperative enhanced inhibition using dual TKIs against MET and EGFR pathways may be an effective treatment strategy to inhibit lung cancer with intrinsic or acquired T790M-EGFR-mediated TKI resistance." (PMID 19238632, 2008). "Recently, it has been demonstrated that mutations in the tyrosine kinase domain region of the EGFR gene in NSCLC predict the response to tyrosine kinase inhibitors and enable the identification of the subpopulation of lung cancers that are likely to respond to drugs targeted to EGFRs." (PMID 17477876, 2007). "The EGFR 181946C>T polymorphism was significantly associated with the risk of lung cancer in the smokers but not in the never-smokers, which reflects a gene-environment interaction." (PMID 17956637, 2007). "The range of relative expression of EGFR compared to ACTB of lung cancer cell lines was variable." (PMID 17455987, 2007). "To study TKI-induced cell death and mechanisms of resistance, we used lung cancer cell lines (with or without EGFR mutations), Ba/F3 cells stably transfected with EGFR mutation constructs, and tumor samples from a gefitinib-resistant patient." (PMID 17973572, 2007). "Our case–control study revealed that lung cancers harbouring EGFR mutation appear to occur independent of tobacco smoking, whereas lung cancers without EGFR mutations are very much dependent on smoking dose." (PMID 17325698, 2007). "In this study we studied BIM's role in TKI-induced apoptosis in EGFR-mutant lung cancers." (PMID 17973572, 2007). "Moreover, enforced expression of mutant EGFR in transgenic mice promoted development of lung carcinomas." (PMID 17973573, 2007). "The preferred and practical method is one that can sensitively, specifically and quickly detect EGFR mutations from specimens used for the diagnosis of lung cancers without removing contaminating normal cells." (PMID 17106442, 2006). "Studies are underway that address the sensitivity of early stage lung cancers to EGFR TKI." (PMID 17096850, 2006). "The data suggest that there is a correlation between the AR and EGFR functions in lung cancer." (PMID 15870715, 2005). "Thus, GMI represents a novel therapeutic strategy to overcome EGFR-TKI resistance in lung cancer." (PMID 41438583, 2026). "Indeed, DORM identifies several non-kinase domain EGFR mutations in lung cancer that have clinical implications identified in patients." (PMID 41567248, 2026). "Lung adenocarcinoma (LUAD), a predominant subtype of non‐small cell lung cancer (NSCLC), is commonly treated with targeted therapies or chemotherapy, depending on the presence of specific driver mutations such as those in the epidermal growth factor receptor (EGFR) gene." (PMID 40856433, 2025). "Furthermore, there are other signaling pathways that regulate PD-L1 expression, such as in lung cancer cells, where PD-L1 expression may be regulated by the epidermal growth factor receptor (EGFR) pathway." (PMID 40297576, 2025). "However, an experimental approach that encompasses both in vitro assays using EGFR-expressing lung cancer cell lines and in vivo validation—providing a comprehensive understanding of the potential therapeutic implications of caffeic acid in suppressing lung cancer metastasis—is absolutely needed." (PMID 41155483, 2025). "Bladder tumour cells with the presence of reduced SNF5 expression show increased sensitivity to gefitinib, FDA approved EGFR‐targeted drug for lung cancer treatment, EGFR‐targeted drugs may be an effective approach for treating SNF5‐deficient bladder cancer associated with drug resistance." (PMID 39779467, 2025). "Translating findings on PM2.5 exposure, EGFR mutations, inflammation, and oxidative stress into clinical practice involves creating comprehensive screening and early detection guidelines tailored for nonsmokers at risk of lung cancer." (PMID 39578555, 2025).